SLC26A3 (solute carrier family 26 member 3)
Diseases named in the same sentence as SLC26A3 in open-access papers (continued):
Sharing a sentence is not in itself a finding about the gene and the disease.
intestinal disease (3 papers, 2016 to 2024). "Mutations in the two major HCO3− exit pathways into the lumen, namely CFTR and DRA (Slc26a3), cause severe intestinal disease in humans, and the corresponding gene knockout is lethal for mice, pigs, and ferrets due to their intestinal phenotypes." (PMID 27228994, 2016).
genetic disorder (2 papers, 2021 to 2022). "Congenital chloride-losing diarrhea (CCLD) is a rare genetic disorder due to autosomal recessive mutation in the SLC26A3 gene on chromosome 7." (PMID 34777886, 2021).
psychiatric disease (1 paper, 2025). "Our results also showed that many psychiatric disease-associated remarkable genes, were upregulated (SLC35F1, SNHG5, and FAM118A) or downregulated (SLC26A3, SLC27A4, LINGO1, and RASGEF1B) in PBMCs of patients with WD." (PMID 40384935, 2025).
SLC26A3 also shares sentences with these, for which no sentence is quoted: Pendred syndrome (5 papers); diarrheal disease (4); Bartter syndrome (3); deafness (3); Constipation (2); diastrophic dysplasia (2); hyperaldosteronism (2); inflammation (2); Obesity (2); spermatocele (2); adenocarcinomas of the colon (1); Alzheimer disease (1); Ataxia (1); autosomal recessive disease (1); Barrett esophagus (1); Calcium oxalate nephrolithiasis (1); campylobacteriosis (1); cholangitis (1); chondrodysplasia (1); Chronic diarrhea (1); gastric cancer (1); Gitelman syndrome (1); glioblastoma (1); goiter (1); hepatoma (1); hyperglycaemia (1); ileocolitis (1); infectious colitis (1); infectious diarrhea (1); intestinal inflammation (1).
A further 11 diseases each share a sentence with SLC26A3 in 1 paper.